CXCL8 (C-X-C motif chemokine ligand 8)
Diseases named in the same sentence as CXCL8 in open-access papers (continued):
Sharing a sentence is not in itself a finding about the gene and the disease.
melanoma (continued). "In melanoma, the metastatic potential of CXCL8 depends on its ability to promote vascularization, activate MMP2, and enhance anoikis resistance." (PMID 31304688, 2019). "A study in patients with different types of cancer, including melanoma and thyroid cancer, demonstrated that the serum concentrations of another chemokine, CXCL8, were predictive of tumor burden and extent of disease." (PMID 31762942, 2019). "The authors suggest that the autocrine CXCL8/CXCR2 signaling pathway can escalate melanoma aggressiveness." (PMID 31731811, 2019). "Increased CXCL1, CXCL2, and CXCL8 mRNA in melanoma sEVs, relative to primary melanocyte sEVs, was the most consistent finding." (PMID 30870978, 2019). "Based on these findings, CXCL8 received increasing attention in melanoma patients as an important prognostic tool for estimating patient’s tumor burden and disease-free survival." (PMID 31762942, 2019). "The neutralization of CXCL8 via ABX-IL8 (a blocking antibody) significantly reduced neoplastic cell invasion and angiogenesis in mice bearing a melanoma." (PMID 29977225, 2018). "This conclusion would fit with notions in human melanoma cells, which also bear the BRAF-V600E mutation and respond to a BRAF inhibitor with a reduced synthesis of CXCL8, thus resulting in anti-proliferative and anti-metastatic effects." (PMID 29977225, 2018). "Studies shows that C-X-C motif chemokine ligand 8 (CXCL8) chemokine played an important role in B-cell lymphoma-extra large (BCL-XL) protein overexpression during tumor progression of human melanoma cells in a zebrafish xenograft model." (PMID 30544544, 2018). "As shown in melanoma and in cancers of the liver, pancreas, and colon–rectum, CXCL8 functions as an autocrine growth factor." (PMID 29977225, 2018). "In several types of cancer including melanoma, renal cell carcinoma, non-small cell lung cancer, and hepatocellular carcinoma, the levels of CXCL8, as measured in serum and in tissues, correlate with tumor size, depth of infiltration, stage, and prognosis." (PMID 29977225, 2018). "This is in agreement with previously published data, showing that IM upregulates CXCL8 in keratinocytes, fibroblast, neutrophils and melanoma cells in vitro as well as MIB-2, the murine homologue of CXCL8, in IM-treated mouse skin." (PMID 30266096, 2018). "All of these observations reinforce the concept that Gro-family chemokines and CXCL8 (IL-8) act as paracrine and autocrine mediators on melanoma growth and progression." (PMID 28129639, 2017). "We previously demonstrated that BCL-XL also promotes tumor angiogenesis through the NF-kB/CXCL8 axis both in melanoma and glioblastoma models." (PMID 29238043, 2017). "Studies have also shown that CXCL8, CXCR1, and CXCR2 have been associated with tumor progression in melanoma by means of affecting the growth of the tumor cells, angiogenesis, and metastasis." (PMID 27379162, 2016). "Fifth, low TTP levels in mutant BRAFV600E-driven melanoma triggers increased levels of IL-8 (CXCL8), tumor growth, and angiogenesis." (PMID 27825143, 2016). "In several cell lines including those derived from melanoma, BCL-XL has been implicated in the pro-angiogenic phenotype of cancer cells by regulation of CXCL8 expression." (PMID 26035829, 2015). "CXCL8 signaling has also been shown to promote migration and invasion in melanoma, colon and gastric cancer." (PMID 24276377, 2013). "CXCL8 is not only known to promote the proliferation of prostate cancer cells; studies from other laboratories have demonstrated CXCL8-induced proliferation in colon, non-small cell lung cancer and melanoma cell lines." (PMID 24276377, 2013). "We have demonstrated here that senescent melanoma cells secrete IL-6, IL-8 [CXCL8] and GRO [CXCL1, 2 and 3] in vitro and in vivo, which are associated with the pro-inflammatory response and recruitment of neutrophils and macrophages to senescent tumour cells." (PMID 23180582, 2013).
melanoma (continued). "The multiple CXCL-8-regulated biological activities in endothelial cells provide an underlying mechanism for our current findings that modulation of CXCL-8 levels affects melanoma angiogenesis." (PMID 23342280, 2012). "In this study, we evaluated the critical role of CXCL-8 in melanoma growth and progression by modulating its expression in melanoma cell lines expressing different levels of CXCL-8." (PMID 23342280, 2012). "On the other hand, suppressing the CXCL-8-dependent pathway provides a valid rationale for melanoma therapy." (PMID 23342280, 2012). "Taken together, our data show that modulation of CXCL-8 levels affects the clonogenic and growth potential of melanoma cells." (PMID 23342280, 2012). "CXCL-8, induced by factors such as ultraviolet B irradiation, contributes to increased melanoma burden in nude mice." (PMID 23342280, 2012). "Even though chemokines have gained attention, the knowledge regarding the direct involvement of CXCL-8 in melanoma progression is not completely understood." (PMID 23342280, 2012). "Inhibition of CXCL-8 signaling or its receptors shows therapeutic efficacy against melanoma in preclinical studies." (PMID 23342280, 2012). "CXCL-8, a chemokine secreted by melanoma and stromal cells, serves as a growth and angiogenic factor for melanoma progression." (PMID 23342280, 2012). "More important, we demonstrated that serum CXCL-8 level correlates with tumor burden and spontaneous lung metastasis in melanoma-bearing mice." (PMID 23342280, 2012). "Our previous studies found a positive correlation between CXCL-8 and its receptor expression and melanoma aggressiveness." (PMID 23342280, 2012). "Our recent studies have demonstrated that CXCR1 and CXCR2, receptors of CXCL-8, are functionally involved in melanoma progression." (PMID 23342280, 2012). "In contrast, the incidence of spontaneous lung metastasis of highly metastatic A375SM melanoma cells was greatly inhibited when CXCL-8 was downregulated." (PMID 23342280, 2012). "We observed significant correlation between serum CXCL-8 level and melanoma burden and spontaneous metastasis, demonstrating serum CXCL-8 as an important preclinical diagnostic marker." (PMID 23342280, 2012). "This study evaluated how modulation of CXCL-8 levels in melanoma cell lines with different tumorigenic and metastatic potentials affected multiple tumor phenotypes." (PMID 23342280, 2012). "CXCL8, acting as an autocrine/paracrine growth factor, influences the process of melanoma progression by activating its receptors, CXCR1 and CXCR2." (PMID 24212647, 2011). "The expression of CXCL8 in melanoma, as well as its receptors CXCR1 and CXCR2, has demonstrated a positive correlation with disease progression." (PMID 24212647, 2011). "Our previous results have demonstrated that CXCL-8 is a paracrine and autocrine angiogenic factor and CXCL-8-mediated angiogenesis is an important step in melanoma growth." (PMID 19401689, 2009). "The expression of CXCL-8 in melanoma has been shown to correlate positively with disease progression." (PMID 19401689, 2009). "The aggressiveness of malignant melanoma is attributed, in part, to the expression of CXCL-8 and its receptors, CXCR1 and CXCR2." (PMID 19401689, 2009). "Here, we have also demonstrated that overexpression of CXCR1 or CXCR2 in CXCL-8-expressing melanoma cells potentiates ERK1/2 MAP kinase signalling." (PMID 19401689, 2009). "On the other hand, a recent report suggests that in melanoma cells, CXCL-8-mediated chemotaxis is mainly mediated through CXCR1." (PMID 19401689, 2009). "These chemokines have previously been shown to stimulate melanoma cellular proliferation and CXCL1 and CXCL8 were shown to be involved in invasion and metastasis of melanoma cells." (PMID 17261188, 2007). "CXCL8 has been shown to be mitogenic for cancers such as melanoma, colon cancer, pancreatic cancer, malignant mesothelioma and Kaposi's sarcoma." (PMID 15545974, 2004).
melanoma (continued). "Genistein also blocks the proliferation of melanoma cells by reducing CXCL8 levels." (PMID 40076892, 2025). "Similarly, melanoma cells respond to dacarbazine by a high level of CXCL8 in a NF-κB-dependent manner." (PMID 40076892, 2025). "Moreover, their inhibition led to a reduction in key pro-inflammatory cyto-chemokines genes, such as CCL2, IL6, and CXCL8, regulated by NFkB-mediated transcription and contributing to melanoma cell survival and to immunosuppressive TME." (PMID 41550951, 2025). "Early Studies recognized that tumor cell lines produced CXCL8 or its homologous factors and CXCL8 could promote the growth and development of various tumors, including melanoma, gastric cancer, lung cancer." (PMID 38786066, 2024). "Targeting CXCL8 or its receptors could, therefore, be a promising strategy to inhibit melanoma progression and improve patient outcomes." (PMID 39200315, 2024). "In addition, the inhibition of the CXCR1,2/CXCL8 axis in mouse models reduced melanoma infiltration by neutrophils, tumour growth, angiogenesis and metastasis." (PMID 37170733, 2023). "In addition to the effect of the CXCR1,2/CXCL8 axis in melanoma cells, it also plays an essential role in immune regulation as CXCR1 and CXCR2 are expressed on neutrophils, correlating with poorer prognosis and poor response to checkpoint inhibition." (PMID 37170733, 2023). "In addition, serum levels of myeloperoxidase, matrix metalloprotease-9, CXCL8/IL-8, granulocyte and monocyte colony-stimulating factor and NETs were significantly increased in patients with advanced melanoma compared to healthy controls." (PMID 37525065, 2023). "Melanoma patients may benefit from treatments that block CXCL-8 signaling or its receptor, according to preliminary research." (PMID 37215082, 2023). "However, CXCL1, CXCL2, CXCL3, CXCL5 and CXCL8 mRNAs were significantly upregulated in melanoma samples compared to benign nevi." (PMID 37270599, 2023). "Interestingly, these authors also observed higher levels of autophagy and protein secretion, such as CXCL8 and IL-1β, in metastatic melanomas in comparison to cells derived from primary lesions." (PMID 35008395, 2022). "ABX-CXCL8, a CXCL8 blocking antibody, inhibited melanoma growth in a xenograft model." (PMID 33603130, 2022). "In melanoma, a high expression of this gene was correlated with the increased secretion of IL1β, CXCL8, LIF, FAM3C, and DKK3 in vitro, and metastatic melanoma patients with elevated tumor autophagy were shown to present higher levels of these proteins in their plasma." (PMID 35008395, 2022). "To further investigate the involvement of Bcl-xL in angiogenesis, we also analyzed whether the Bcl-xL/CXCL8 pathway was important to promote angiogenesis and aggressiveness in zebrafish melanoma models." (PMID 33803452, 2021). "Aside from its direct effect on melanoma cells, CXCL8, along with other ligands of CXCR1 and CXCR2, namely CXCL1-3 and CXCL5-7, recruit innate cells, most notably neutrophils, which express the receptors CXCR1 and CXCR2 and are the “first responders” to tissue injury and damage." (PMID 34830780, 2021). "Finally, via microarray and RNA seq public databases, a correlation between CXCL8 and markers of melanoma aggressiveness was also identified, together with a correlation between Bcl-xL and CXCL8 expression and poor prognosis of melanoma patients." (PMID 33803452, 2021). "CXCL8 could be a serum biomarker by which to predict clinical benefit from immune checkpoint blockade in melanoma and NSCLC patients." (PMID 35011369, 2021). "Finally, expression of IL6 and CXCL8 was also significantly reduced by stable knockdown of p16 in melanoma cells induced to senesce using etoposide." (PMID 33550279, 2021). "It shows that CXCL8 is an important biomarker in the process of melanoma metastasis." (PMID 32894090, 2020). "In malignant melanoma, the expression of CXCL8 and CXCR2 promotes aggressive growth and metastasis." (PMID 33336008, 2020).
melanoma (continued). "As IL-8 can regulate different cellular programs, including invasion/migration and angiogenesis, and AG significantly downregulated expression of CXCL8 and reduced the amount of IL-8 protein secreted by melanoma cells, we aimed to assess the influence of AG on other regulators of these processes." (PMID 32466509, 2020). "Constitutive activation of ERK might downregulate tristetraprolin, a crucial protein responsible for the stability of IL8/CXCL8 mRNA in melanoma." (PMID 32997401, 2020). "Interestingly, exposure to UVB radiation, which is a major risk factor for melanoma, induces the production of CXCL1 and CXCL8 in the epidermis, thus supporting the recruitment of neutrophils with anti-cancer activity." (PMID 33171792, 2020). "CXCL8, also known as interleukin 8 (IL-8), acts as a melanoma cell mitogen and growth factor." (PMID 30870978, 2019). "Owing to its potent pro-inflammatory properties, CXCL8 expression in normal tissues is low or undetectable, while an increased expression of CXCL8 was detected in several human solid tumors such as melanoma, squamous cell carcinoma, cervical, ovarian, non-small cell lung, colon, and gastric cancers." (PMID 29977225, 2018). "CXCL8 has a well-established role in mediating initiation and development of various cancers, including breast, prostate and lung cancer, colorectal carcinoma, and melanoma." (PMID 30591657, 2018). "Furthermore, TTP depletion increased the production of several chemokines, such as C-X-C motif chemokine ligand 1 (CXCL1), CXCL2, and CXCL8 (also known as IL-8), which are involved in melanoma pathogenesis and angiogenesis." (PMID 30380668, 2018). "One way is direct inhibition via neutralizing antibodies for CXCL8, which were mainly developed for the treatment of inflammatory diseases like chronic obstructive pulmonic disease, but which also did show promising results in pre-clinical melanoma models." (PMID 26674118, 2015). "CXCL8 expression correlates with metastatic potential in human melanoma and ovarian cancer cells." (PMID 23586055, 2013). "In order to examine the preclinical prognostic significance of CXCL-8 level in melanoma growth and metastasis, we examined the serum CXCL-8 levels and determined whether there is any correlation between them." (PMID 23342280, 2012). "In this study, we evaluated the direct involvement of CXCL-8 in melanoma progression." (PMID 23342280, 2012). "CXCL-8, hardly detectable in normal cells, is constitutively secreted by melanoma cells." (PMID 23342280, 2012). "Moreover, an increase in chemotaxis and chemoinvasion of human melanoma cells expressing CXCR1 or CXCR2 on stimulation with CXCL-8 was also observed." (PMID 19401689, 2009). "Similar results were observed in SBC-2-transfected cells (data not shown) Together, these results demonstrate that overexpression of CXCR1 or CXCR2 in SBC-2 and A375P melanoma cells leads to CXCL-8-induced activation of ERK1/2 MAP kinase, which facilitates increased cell growth and motility." (PMID 19401689, 2009). "On the other hand, CXCL8 showed a variable expression pattern with no strong association with melanoma cell invasiveness; however, the highest expression was found in HHSEC cells co-cultured with the WM3248 cell line, which had the highest increased invasiveness of all cell lines." (PMID 37240247, 2023). "In addition, overexpression of CXCL8 enhanced growth and metastasis in human melanoma." (PMID 35321317, 2022). "Interestingly, a novel lncRNA (ENSG00000285534) is downregulated in both sets of R2-R2_pt and R4-R4_pt, whereas CXCL8 (C-X-C motif chemokine ligand 8 (ENSG00000169429)), which is associated with melanoma and bronchiolitis is downregulated in R5-R5_pt and upregulated in R6-R6_pt." (PMID 36360315, 2022).
melanoma (continued). "When this chemokine axis is inhibited in mouse models, melanoma infiltration by neutrophils is reduced, and reduced tumour growth, angiogenesis, and metastasis is seen, suggesting that neutrophils contribute to the protumour properties of CXCL8 and its receptors." (PMID 34830780, 2021). "However, although CXCL8 protein levels in both tumors and blood sera have been shown to correlate with tumor progression in melanoma patients, its expression in colon cancer patients has conversely been associated with a significant increase of overall post-operative survival." (PMID 30591657, 2018). "CXCL8 (IL-8) signaling has been implicated in STAT3 activation and nuclear translocation, suggesting that inhibition of CXCR1/2 may also lead to the inhibition of STAT3 in melanoma cells." (PMID 28129639, 2017). "Similarly, CXCL-8 regulates the process of melanoma cell local migration and distant metastasis." (PMID 23342280, 2012). "However, the functional significance of CXCR1 and CXCR2 and its ligand CXCL-8 in melanoma progression remains unclear." (PMID 19401689, 2009). "Accordingly, among the genes investigated, CXCL8 and CTLA4 were identified as significantly upmodulated genes in melanoma cultures." (PMID 41596411, 2026). "Hypoxia-induced CXCL8 in ESCA recruits MDSCs and upregulates PD-L1, paralleling its role in melanoma and CRC, where CXCL8 drives neutrophil/MDSC recruitment and angiogenesis, underpinning anti-PD-1 resistance." (PMID 40134607, 2025). "Neutrophil recruitment is mainly mediated by chemokines with glutamate-leucine-arginine motifs (ELR+ chemokines), mainly melanoma growth-stimulating activity (CXCL1, CXCL2), epithelial neutrophil activating protein (CXCL5), interleukin-8 (CXCL8)." (PMID 40191727, 2025). "Meanwhile, IL-8, also known as CXCL8, encourages the epithelial–mesenchymal transition (EMT) in melanoma cells, a process where epithelial cells acquire mesenchymal characteristics and increased migratory ability." (PMID 40636453, 2025). "CXCL1 from malignant melanoma cells also acts on keratinocytes together with bFGF, CXCL8/IL-8, and VEGF-A." (PMID 38673949, 2024). "Overexpression of GLI1 in A375 melanoma cells drastically downregulated CCL7, CCL2, CCL20 and CXCL8 mRNA level." (PMID 39090759, 2024). "Serum levels of IL-6, CXCL8 and CCL2 in particular, surge during melanoma progression, while mature NKp44+ ILC3s protect against melanoma." (PMID 38410760, 2024). "Immunomodulatory CAFs (iCAFs) displayed high expression of MMP1, MMP3, IL6, CXCL8, and IDO1, and included CAFs from melanomas, 1 SCC, and 1 BCC." (PMID 38525245, 2024). "The major chemokine/chemokine receptor interactions occurring in melanoma development and progression include the CXCR4/CXCR7/CXCL12, CXCR3/CXCL9,10,11, CXCR1,2/CXCL8, CCR2/CCL2, CCR4/CCL17,22, CCR5/CCL5, CCR7/CCL21 and CCR10/CCL27 axes." (PMID 37170733, 2023). "This analysis revealed 15 differentially expressed proteins (including CD31, VCAM-1, ANGPT2, CXCL8, and CCL20) in the hepatic endothelial cells after co-culture with melanoma cells." (PMID 37240247, 2023). "Large quantities of CXCL8/IL-8 and CXCL1/Groα were constitutively released in melanoma CM (~ 8 ng/ml and ~ 2 ng/mL, respectively)." (PMID 37525065, 2023). "IL-6, CXCL8 and VEGF have been widely demonstrated to be related to worse clinical outcome in melanoma." (PMID 35173725, 2022). "Neutrophils of the tumour inflammatory infiltrate increase during melanoma progression, their accumulation depending on CXCL1, CXCL2, CXCL3, CXCL5, and CXCL8 molecules, which are stimulated by UV radiations." (PMID 35334544, 2022). "Particularly, serum levels of IL-6, CXCL8 and CCL2 have been previously shown to increase during melanoma progression." (PMID 35173725, 2022). "Autophagy secreted proteins, such as IL‐1β, CXCL8, LIF, are shown to be elevated in high‐autophagy melanoma cell lines." (PMID 36124714, 2022).